IL6 (interleukin 6)
Diseases named in the same sentence as IL6 in open-access papers (continued):
Sharing a sentence is not in itself a finding about the gene and the disease.
Kawasaki disease (30 papers, 2011 to 2026). A rare inflammatory disease characterized by an acute febrile, systemic, self-limiting, medium-vessel vasculitis primarily affecting children. "The association of Kawasaki disease with cytokines including IL-6, IL-8, and IL-17, has been mentioned in several studies." (PMID 39985017, 2025). "Studies have found that IL-6 can serve as a potential biomarker for the early diagnosis of Kawasaki disease (KD)." (PMID 39318622, 2024). "In our previous research we have found that patients with Kawasaki disease had higher levels both M1 related cytokine TNF-α, and the M2 related cytokines IL-6, IL-4 and IL-13 in the acute phase of Kawasaki disease, which decreased after IVIG therapy." (PMID 35154107, 2022). "Typically, interleukin (IL)-6 is predominantly increased, whereas other inflammatory parameters remain within relatively low or normal levels in acute Kawasaki disease." (PMID 35778759, 2022). "The KDSS in acute phase of Kawasaki disease is IVIG-resistant with higher level of inflammatory cytokines such as IL6, TNFα, and IL1 and good response to methylprednisolone pulses." (PMID 36585531, 2022). "Our data are also consistent with in vivo observations wherein IVIg treatment reduces serum IL-6 and IL-6 production by LPS-stimulated whole blood in children with Kawasaki disease, and reduces serum TNF and IL-1β levels in patients with Guillain-Barré syndrome." (PMID 30515163, 2018). "In Kawasaki disease, similarly to TAK, the inflammatory process is complex, and IL-6, IL-8, TNF-α, IFN-γ, and CRP are involved in the course of the disease." (PMID 37626704, 2023). "For example, IL-6 is higher in HLH driven by auto-inflammatory disorders and Kawasaki disease than that in pHLH and EBV-HLH." (PMID 35296096, 2022). "In NFKD, the IL6, AST, CRP, ESR are in higher levels in comparison with other atypical Kawasaki disease." (PMID 36585531, 2022). "RBC, HB, CK, CK-MB, ALB, A/G, LC3II, ATG16L1 were positively correlated with BECN1; the incidence of IVIG-resistant Kawasaki disease, length of stay, lymph node enlargement, perianal desquamation, CAL, IL-4, IL-6, CRP, PCT, SF, CD3 + CD4 + T, and r-GT were negatively correlated with BECN1." (PMID 38114939, 2023). "In contrast with Kawasaki disease, IL-18 is significantly elevated in the acute phase of sJIA, without exception, whereas IL-6 is increased at variable levels." (PMID 35778759, 2022). "In contrast, serum IL-6 levels were found to be high both in sJIA and Kawasaki disease, but did not increase further when sJIA patients developed MAS." (PMID 21749729, 2011). "Biologic therapies targeting IL-6 and IL-1 have also been reported as being in use for cytokine storm, but the lack of evidence and randomized control trial data on their efficacy in the management of MIS-A means that the therapy is based on the expertise and protocols for Kawasaki disease (KD)." (PMID 37628963, 2023).
myopia (30 papers, 2017 to 2026). "Fourth, changes in Zc3h11a expression were found to cause changes in the myopia-related genes Tgfβ1, Mmp2, and Il6." (PMID 40864167, 2025). "In a mouse model of form-deprivation myopia, IL-6 has been linked to macrophage polarization toward an M2 phenotype, which is associated with extracellular matrix remodeling and fibrotic progression." (PMID 41438149, 2025). "If choroidal IL-6 gene expression is causally related to ocular changes associated with recovery from myopia, then agents known to block recovery should also block choroidal IL-6 upregulation." (PMID 34608867, 2021). "In contrast to MMP-2, which has been well portrayed in scleral remodeling and thinning during experimental myopia studies, IL-6 is seldom implicated in myopia." (PMID 30837544, 2019). "Interestingly, systemic treatment of chicks with the potent anti-inflammatory agent, dexamethasone, significantly reduced choroidal Il6 gene expression in recovering eyes and inhibited the scleral extracellular matrix changes associated with recovery from myopia." (PMID 38390290, 2023). "Furthermore, severe myopia could significantly increase the levels of IL-1 and IL-6, which could be associated with the myopic control mechanism." (PMID 33575355, 2021). "Molecular profiling revealed lower levels of HIF-1α and VEGF (p < 0.01), and elevated levels of PDGF-BB (p < 0.05), HGF, and IL-6 (p < 0.01) in the high myopia group." (PMID 41438149, 2025). "Chronic inflammation, characterized by elevated cytokines like IL-6 and TNF-α, has been implicated in scleral remodeling and thinning, processes central to myopia development." (PMID 40571595, 2025). "Accumulating evidence has revealed that there is an increase of pro-inflammatory factors in myopia models and patients, such as upregulation of IL-1β in the sclera and increased IL-6 levels in aqueous humor." (PMID 41222199, 2025). "Studies show that inflammatory factors like tumor necrosis factor-alpha (TNF-α), interleukin-6 (IL-6), and nuclear factor kappa B (NF-κB) are significantly elevated in myopia models, suggesting a key role for the immune response in myopia development." (PMID 41191163, 2025). "Studies have demonstrated that the MMP-2 and IL6 expression levels are increased in myopic eyes and that inhibiting MMP-2 or IL6 expression will provide some degree of control over myopia progression." (PMID 40864167, 2025). "The abnormal expression of matrix metalloproteinase-2 (Mmp2) and interleukin-6 (Il6) can induce myopia, and these are regulated by NF-κB (Libermann and Baltimore, 1990; Wu and Schmid-Schönbein, 2011)." (PMID 40864167, 2025). "Elevated levels of TNF-α and IL-6 have been observed in tree shrews with myopia and patients with high myopia." (PMID 39239046, 2024). "Significant changes between high myopia and myopia were observed for IL-6, IL-8, and ANG-2 (p < 0.05)." (PMID 37759728, 2023). "Increased levels of IL-6 and IL-8 proteins were found in AH samples collected from both myopia subgroups, as compared to emmetropic ones (respectively, p < 0.05)." (PMID 37759728, 2023). "By suppressing the levels of TNF-α, IL-1β, and IL-6 in human retinal pigment epithelium cells, resveratrol inhibits inflammatory effects to ameliorate myopia development." (PMID 37446088, 2023). "As shown, an upregulation of IL-6 (p < 0.05) and IL-8 (p < 0.05) transcripts was detected in high myopia in comparison to myopia and emmetropia." (PMID 37759728, 2023). "In myopia animal model, expressions of IL-6, IL-8, and TNF-α increase when compared with control eyes." (PMID 36242032, 2022). "In the present study, we report that myopic defocus, either in eyes recovering from induced myopia, or in eyes treated with +15 D spectacle lenses, stimulates IL-6 mRNA and protein synthesis in the chick choroid." (PMID 34608867, 2021). "(A, B) Il-6 was localized in treated and contralateral control eyes after 24 hr of recovery from induced myopia (green labeling)." (PMID 34608867, 2021).
myopia (continued). "(B) IL-6 protein production by control and recovering choroids following 6 and 24 hr of recovery from induced myopia." (PMID 34608867, 2021). "We found that a single intravitreal injection of atropine to chicks undergoing form deprivation-induced myopia stimulated choroidal IL-6 gene expression." (PMID 34608867, 2021). "Previously, we and others have found that inflammatory cytokines such as IL-6, IL-8, and MCP-1 are overexpressed in myopic eyes and associated with myopia progression." (PMID 34285659, 2021). "Furthermore, IL-6, a key inflammatory mediator, has been shown to be upregulated in both human uveitis patients and experimental myopia models, where it plays a crucial role in ocular growth regulation." (PMID 41191163, 2025). "In the vitreous humor, the expression of interferon γ (IFN-γ), IL-6, IFN-γ-induced protein 10 (IP-10), eotaxin, and macrophage inflammatory protein 1α (MIP-1α) was significantly elevated, which may serve as myopia-associated markers." (PMID 41191163, 2025). "In addition, the expression levels of myopia-related factors, such as Tgfβ1, Mmp2, and Il6, were upregulated in the retina and sclera of the Zc3h11a+/- mice." (PMID 40864167, 2025). "Previously, we observed rapid and significant changes in choroidal gene and protein expression of the pro-inflammatory cytokines IL6 and IL1β in response to myopic defocus, either during recovery from myopia or following application of +15D lenses to normal chick eyes." (PMID 38390290, 2023). "Investigations into the retinal and/or RPE expression of these and other factors, known to regulate IL-6 mRNA and protein synthesis, may provide new insights into the visually driven signaling cascade responsible for emmetropization and myopia development." (PMID 34608867, 2021). "Here, we provide evidence that the pro-inflammatory cytokine, interleukin-6 (IL-6), may play a pivotal role in the control of ocular growth using a chicken model of myopia." (PMID 34608867, 2021). "Consistent with previous studies, IL-6 expression was increased by myopia-inducing stimuli." (PMID 33291388, 2020). "Thus, oral administration of LF suppressed lens-induced myopia development by modifying the extracellular matrix remodeling through the IL-6–MMP-2 axis in mice." (PMID 33291388, 2020). "Elevated hypoxia-induced IL-6 has been demonstrated to exacerbate myopia by promoting scleral remodeling through the TGF-β1/Smad2/MMP-2 pathway, supporting the hypothesis that metabolic inflammation contributes to myopia through a “metabolic-immune-hypoxia” network." (PMID 41191163, 2025). "In this context, interleukin-6 (IL-6), a key pro-inflammatory cytokine, has shown a significant positive correlation with axial length (p < 0.01), supporting the hypothesis that inflammation contributes to scleral remodeling and degenerative changes in myopia." (PMID 41438149, 2025). "Moreover, individuals with myopia have been found to exhibit elevated levels of inflammatory factors in the vitreous or aqueous humor, such as interleukin-6 and matrix metalloproteinase-2, indicating low-grade inflammation activation in the ocular microenvironment." (PMID 39703523, 2024). "Additionally, severe myopia may substantially raise IL-1 and IL-6 levels, which may be related to the myopic control mechanism." (PMID 38378527, 2024). "Microarray, real-time RT-qPCR, and ELISA analyses identified IL-6 upregulation in the choroids of chick eyes under two visual conditions that introduce myopic defocus and slow the rate of ocular elongation (recovery from induced myopia and compensation for positive lenses)." (PMID 34608867, 2021). "To determine the precise temporal pattern of IL-6 expression during recovery, we utilized TaqMan real-time PCR to quantify IL-6 mRNA concentrations in choroids following 10 days of form deprivation and over several time points during recovery from induced myopia." (PMID 34608867, 2021).
myopia (continued). "In FDM models, CSA treatment mitigated refractive changes; downregulated c-Fos, IL-6, TNF-α, and NF-κB; and enhanced IL-10 expression, supporting its potential in inflammation-targeted myopia therapy, although further clinical validation is needed." (PMID 41191163, 2025). "Upregulated expression of c-Fos, nuclear factor κB (NF-κB), interleukin (IL)-6, and tumor necrosis factor (TNF)-α were demonstrated from an experimental myopia model." (PMID 41224847, 2025). "Upregulated IL-6 activated the TGF-β1/Smad2/MMP-2 pathway and promoted transdifferentiation of human scleral fibroblasts, resulting in sclera thinning and myopia progression." (PMID 41224847, 2025). "The levels of IL-6 and CCL2 in the tears from patients with high myopia were significantly increased, and correlated with the severity of myopic maculopathy." (PMID 40909333, 2025). "These inflammatory factors are significantly elevated in both animal models and clinical samples of myopia, and they activate inflammatory mediators, such as TNF-α and IL-6, primarily through the NF-κB signaling pathway." (PMID 41191163, 2025). "Similar results have been validated in animal studies, where the induction of myopia leads to increased TGF-β and matrix metalloproteinase-2 (MMP-2) expression, accompanied by significant increases in IL-6, IL8, TNF-α and MCP-1." (PMID 41191163, 2025). "T1DM can decrease accommodation of the lens and ciliary muscles, leading to myopia, and T2DM, an inflammatory disease that leads to elevated IL-1β, IL-6, TGF-β, and TNF-α levels, can also exaggerate myopia progression." (PMID 39006849, 2024). "Meanwhile, CSA can decrease c-Fos, IL-6, TNF-α, and NF-κB expression and increase IL-10 immunoreactivity, suggesting that anti-inflammatory agents can effectively slow myopia progression." (PMID 39006849, 2024). "Studies have shown that prolonged inflammation can exacerbate myopia by enhancing the expression of inflammatory components such as MMP-2, TGF-β, IL-1β, IL-6, and TNF-α." (PMID 39006849, 2024). "Animal models of experimental myopia showed that FJE, PVE, and FJE plus PVE treatments inhibited axial elongation, as well as NF-κB, TGF-β, IL-1β, IL-6, IL-8, and TNF-α inflammatory factors and collagen expression." (PMID 39006849, 2024). "Reports show that high levels of IL-6 and TNF-α inflammatory cytokines initiate ocular inflammation and promote myopia progression in hamsters." (PMID 34285659, 2021). "Recent clinical and experimental studies provided evidence showing that atropine induced the downregulation of c-Fos, NF-κB, interleukin (IL)-6, and tumor necrosis factor (TNF)-α expression in hamsters with monocular form deprivation (MFD)-induced myopia." (PMID 34287272, 2021). "While the progression of myopia was enhanced through the treatment of lipopolysaccharide (LPS) or peptidoglycan (PGN), the expression level of IL-6, TNF-α, c-FOS, and nuclear factor κB increased." (PMID 28828383, 2017). "Furthermore, recent experimental studies have reported that atropine reduces inflammatory markers such as c-Fos, NF-κB, IL-6, and TNF-α in form-deprivation myopia models, while promoting COL-1 expression." (PMID 41191163, 2025). "We postulate that the expression of inflammatory markers, including NF-κB, TGF-β, IL-1β, IL-6, IL-8, and TNF-α, may contribute to the chronic inflammatory state observed in myopia." (PMID 39006849, 2024). "Furthermore, the authors reported a significant inverse correlation between myopia degree and both VEGF and IL-6 levels." (PMID 39597899, 2024). "In addition, there is a strong positive correlation between ocular axial length and the expression levels of IL-6 and MMP-2 in patients with high myopia." (PMID 36700118, 2023). "In our study, we found that IL-6, IL-8, and TNF-α expressions were higher in the myopia eye." (PMID 36242032, 2022).
myopia (continued). "In addition, previous research showed that myopia progression was slowed down by cyclosporine A (CSA) and CSA treatment further reduced the expression of IL-6, TNF-α, c-FOS, and NF-κB in the eye." (PMID 34285659, 2021). "In order to study the effect of resveratrol on the PI3K–AKT, MAPK, and NFκB pathways, involved in myopia progression, ARPE-19 cells were incubated with TNF-α, IL-6, and IL-1β, alone and with combinations of these cytokines, for 10 min prior to the 10 min treatment with resveratrol." (PMID 34287272, 2021). "Thus, a vicious cycle develops between continuously induced TNF-α, IL-6, and IL-1β inflammatory responses in the RPE cells that would affect the levels of IL-6, IL-8, and MCP-1 intraocularly, which would promote myopia progression." (PMID 34285659, 2021). "In conclusion, oral administration of LF can prevent negative-lens-induced myopia in mice by suppressing the IL-6–MMP-2 axis and collagen 1a1 degradation." (PMID 33291388, 2020). "Therefore, IL-6 should be interpreted as an exploratory marker rather than a definitive biomarker in the context of high myopia." (PMID 41438149, 2025). "Furthermore, RPE cells contribute to myopia progression by secreting inflammatory cytokines such as TNF-α and IL-6, which are upregulated in allergic conjunctivitis and have been shown to disrupt epithelial barriers and promote ocular tissue remodeling leading to axial elongation." (PMID 41191163, 2025). "Although the AUC of IL-6 and MCP-1 in tears to predict myopic macular degeneration were below 0.8, further studies on tears might provide more information on biomarkers and pathogenesis of myopia." (PMID 39597899, 2024).
necrotizing enterocolitis (30 papers, 2014 to 2026). Necrotizing enterocolitis (NEC) is a devastating disease that affects mostly the intestine of premature infants. "Symptoms of necrotizing enterocolitis (NEC) were associated with elevated levels of IL-6, while the development of cerebral intraventricular hemorrhage in neonates correlated with high CXCL-5 (p = 0.037) and sepsis was associated with high IL-10 levels (p = 0.02)." (PMID 40244141, 2025). "Administration of adipose tissue-derived stem cells before the onset of the disease lowers the levels of inflammatory cytokines IL-1 and IL-6 in the rat model of necrotizing enterocolitis." (PMID 39456833, 2024). "The onset of NEC initiates a significant cytokine response at both the mucosal and systemic levels, including IL1 and IL6 elevation, among many other factors, being consistent with the overall picture of necrotizing enterocolitis." (PMID 39767803, 2024). "In the experimental necrotizing enterocolitis model it has been shown that BA increases antioxidant mechanisms and decreases pro-inflammatory IL-6 and TN-α." (PMID 33984895, 2021). "For example, in human necrotizing enterocolitis, XBP1 splicing levels correlate with the severity of mucosal damage that is associated with increased mucosal expression of pro-inflammatory cytokines, IL-6 and IL-848." (PMID 29891850, 2018). "It has also been reported to inhibit inflammation in the intestinal epithelium and systemic production of interleukin-6 and interferon-γ, reducing the incidence of necrotizing enterocolitis (NEC)." (PMID 29911097, 2018). "Administration of adipose-derived stem cells before the onset of the disease lowers the initial levels of IL-6 and TNF-alpha in the rat model of necrotizing enterocolitis." (PMID 40724804, 2025). "Likewise, a reduction in the expression of IL-6 was observed in a mice model of necrotizing enterocolitis (NEC) when comparing raw and pasteurized human milk EVs45." (PMID 37344543, 2023). "Also, plasma levels of cytokines like IL-6, IL-8/CXCL8, and IL-10, among others, are elevated during necrotizing enterocolitis." (PMID 39456833, 2024). "The administration of adipose tissue-derived stem cells after the onset of necrotizing enterocolitis did not reduce the levels of inflammatory cytokines IL-1 and IL-6, nor did it influence the histopathological outcomes of the disease in a rat model of NEC." (PMID 39767803, 2024). "Recent research has also shown that SFN (20 mg/kg/day) mitigates necrotizing enterocolitis (NEC) by reducing the expression of IL-1β, IL-8, IL-10, IL-6, and TNF-α, thereby decreasing apoptosis in NEC-induced mice." (PMID 38671854, 2024). "The CRP, IL-6, IL-10, and IFN-γ in the serum of Necrotizing enterocolitis (NEC) intestinal stenosis patients were significantly higher than the reference values." (PMID 35958178, 2022).